GADD45A (growth arrest and DNA damage inducible alpha)
Diseases named in the same sentence as GADD45A in open-access papers (continued):
Sharing a sentence is not in itself a finding about the gene and the disease.
tumor (continued). "Emerging functional evidence implies that GADD45 proteins serve as tumor suppressors in response to diverse stimuli and our results support this notion as GADD45α inhibited SPDEF degradation and thereby reduced migration and invasion." (PMID 26885618, 2016). "GADD45A overexpression can induce tumor cell apoptosis and decrease tumor cell proliferation, survival and tumorigenesis." (PMID 26655928, 2015). "Other studies have shown that Gadd45a inhibits tumor angiogenesis via blocking of the mTOR/STAT3 pathway." (PMID 24658029, 2014). "Gadd45a functions as a tumor suppressor in Ras-driven breast tumorigenesis by increasing JNK-mediated apoptosis and p38-mediated senescence." (PMID 23706118, 2013). "GADD45a mRNA and protein levels were increased significantly in tumor tissue than that in adjacent normal tissue." (PMID 22313682, 2012). "Accumulating evidence suggests that FoxO act as tumor suppressors, inhibiting tumor growth by the activation of genes such as Bim, FasL, p27kip, cyclin D, GADD45a, glucose-9-phosphatase, and manganese dismutase." (PMID 23259070, 2012). "GADD45A was successfully sequenced for 38 samples (17 normal epithelium samples and 21 tumor samples)." (PMID 20444249, 2010). "GADD45A, a potent inhibitor of the c-Jun N-terminal kinase (JNK) cascade and NFKBIA, inhibits transcription factors associated with tumor growth and was up-regulated by doxorubicin in 12 probes." (PMID 18959781, 2008). "GADD45G and GADD45A are regulators of the cell-cycle at the G2/M transition and act as tumor suppressors." (PMID 18847459, 2008). "Based on these exploratory findings, best subset selection identified a two-gene transcriptomic candidate signature comprising PMAIP1 and GADD45A, which showed promising discriminative performance in internal cross-validation and an external tumor-versus-adjacent validation cohort." (PMID 42278359, 2026). "GADD45A is a well-known tumor suppressor involved in DNA damage response, and its downregulation could impair stress responses." (PMID 41009685, 2025). "Aside its well-established tumor suppressor activity, recent studies point to additional roles for GADD45A, including the regulation of catabolic and anabolic pathways, or the prevention of inflammation, fibrosis, and oxidative stress in some tissues and organs." (PMID 40301189, 2025). "Moreover, the GADD45A protein plays a crucial role in tumor proliferation, invasion, metastasis, angiogenesis, chemotherapy resistance, radiotherapy resistance, and clinical prognosis." (PMID 39458909, 2024). "Another study demonstrated that the anti-tumor effect exerted by lemon-derived vesicles in gastric cancer cells could be related to their ability to increase the expression of GADD45A, a tumor suppressor involved in cell cycle control and DNA repair." (PMID 38790792, 2024). "Furthermore, accumulating evidence suggests that the anti-cancer activities of chemotherapeutic agents and non-steroidal anti-inflammatory drugs depend on up-regulation of GADD45A, which induces cell cycle block and apoptosis in tumor cells." (PMID 38822363, 2024). "The top-scoring genes altered in the four gene sets included many genes associated with cell apoptosis and DNA damage, such as GADD45A, DDIT3, BAX, CASP1, CASP8, ATM, and FANCD2, demonstrating that diminishment of RAD51 contributes to the tumor suppressive effect." (PMID 37175611, 2023). "Functional verification in our experiments indicated that Egr1 could be a critical factor in the tumor suppressor pathway, capable of activating the downstream gene Gadd45a to induce cell apoptosis." (PMID 38248651, 2023). "ST suppressed PC cell proliferation in vivo and increased GADD45A expression in tumor tissues." (PMID 35281859, 2022). "Moreover, compared with DMSO treatment, ST treatment significantly decreased the expression of KI67 and increased the expression of GADD45A in tumor tissues." (PMID 35281859, 2022). "GADD45A was gradually considered as a promising target for tumor malignancy." (PMID 35308218, 2022).
tumor (continued). "Additionally, evidence suggests that several drugs with anti-tumor activity based on GADD45A upregulation can induce cell apoptosis in some tumor cells." (PMID 35281859, 2022). "Results from real-time PCR exerted that GADD45A was lowly expressed in tumor tissues, and MA treatment could enhance GADD45A expression dose-dependently in vivo." (PMID 35308218, 2022). "In addition, the expression of two tumor-suppressor genes—IL-24 and GADD45A—was upregulated in E2-treated PDXs, as well as in organoids that were isolated from E2-treated tumors, depending on treatment time." (PMID 34944995, 2021). "Besides, the combination treatment also significantly increased the mRNA levels of TRAF3 and GADD45A and the protein levels of TNFα, TRAF3 and GADD45A in the tumor tissues of these mice." (PMID 34025421, 2021). "These two works suggest that GADD45A may function as either a tumor promotor or suppressor, depending on the kind of oncogenic stress, and these two functions are mediated by different signaling pathways." (PMID 32013256, 2020). "Since MDA-MB-231 and SUM-159 have activating mutations in KRAS and HRAS respectively, it is possible that GADD45A could be functioning as a tumor suppressor in these cell lines." (PMID 28235006, 2017). "Notably, in mammary breast cancer models, Gadd45a behaves as a tumor suppressor in response to H-RAS, and as an oncogene in response to Myc." (PMID 28086219, 2017). "The association of GADD45A polymorphisms with tumor susceptibility and prognosis has never been reported." (PMID 26422378, 2015). "When patients where subdivided into two different groups according to the diagnosis of neoplastic disease (ALL/NHL vs AML) we found a statistically significant difference of Gadd45a (p < 0.0001), pJNK (p = 0.0001), and Caspase8 (p = 0.004) between AML and ALL/NHL patients." (PMID 19298651, 2009). "Ras-driven tumor formation in the absence of Gadd45a resulted in both a decrease in apoptosis, linked to a decrease in JNK activation, and a decrease in senescence, correlated with a decrease in p38 kinase activation." (PMID 18789159, 2008). "Thus, based on the results of transcriptomic sequencing, our finding showed that NF113 may exerts its anti-tumor effect by increasing GADD45A levels." (PMID 39458909, 2024). "Moreover, in terms of the 5-year survival rate, we found that RCC patients with higher GADD45A tumor expression had significantly better outcomes than those with lower expression, further implicating the potential of GADD45A as a predictor of outcomes in RCC patients." (PMID 39451232, 2024). "Finally, CCK-8 assay, wound healing assay, and xenograft tumor model were used to determine the relationship between ST and growth arrest and DNA damage-inducible alpha (GADD45A; the key target of ST) and malignant biological properties of PC in vitro and in vivo." (PMID 35281859, 2022).
tumor (continued). "More recent studies indicated GADD45A could even act as a tumor suppressive gene by facilitating apoptosis, maintaining cell-to-cell adhesion, inhibiting angiogenesis, modulating drug resistance, suppressing metastasis, promoting DNA repair, and stabilizing genomics." (PMID 35308218, 2022). "The fact that GADD45B and GADD45A were significantly overexpressed in both cell lines after fisetin treatment could explain that induction of cell cycle arrest was among mechanisms modulating the anti-tumor activity of fisetin on cancer cell lines." (PMID 28052097, 2017). "Thus, we hypothesized that this variant might disrupt transcription factor binding sites, thereby altering GADD45A expression and affecting tumor genesis." (PMID 26422378, 2015). "After the SH intervention, the levels of the tumor angiogenesis-related genes MMP-2, VEGFA, VEGFC, VAV2, and LARP1 were significantly downregulated when compared with the Model group, whereas the GADD45A level was markedly upregulated." (PMID 41444284, 2025). "GADD45A is downregulated in various tumors such as NSCLC, and its downregulation leads to sustained cell cycling after DNA damage, resulting in increased tumor cell heterogeneity." (PMID 37256211, 2023). "FOXOs are discovered as a tumor suppressor through activating G2/M arrest related genes CDKN1A and GADD45A, apoptosis related genes FAS, DR4 and DR5, respectively 58-62." (PMID 35813464, 2022). "GADD45A acts as a proapoptotic protein that induces apoptosis and cell cycle arrest, and TXNIP is an effector in glucose metabolism and can thus inhibit tumor cell proliferation through glucose metabolism." (PMID 35915803, 2022). "In pathway in cancer and cell cycle, Bcl2, VEGFA, PTEN, Jun, Fos, APC2 were up-regulated and Ccna2, Cdc25a, Mcm3, Mcm6, Ccnb2, Mcm5, Cdk1, Gadd45a, Myc were down-regulated in the MMQ tumor stem-like cells." (PMID 28163656, 2017). "Bcl2, VEGFA, PTEN, Jun, Fos, APC2 were up-regulated and Ccna2, Cdc25a, Mcm3, Mcm6, Ccnb2, Mcm5, Cdk1, Gadd45a, Myc were down-regulated in MMQ tumor stem-like cells group." (PMID 28163656, 2017). "The present analysis showed, for the first time, that the anti-tumor effect of fisetin was mediated mainly through activation of CDKN1A, SEMA3E, GADD45B and GADD45A and down-regulation of TOP2A, KIF20A, CCNB2 and CCNB1 genes." (PMID 28052097, 2017). "Previous studies have shown that downregulation of GADD45A and GADD45G enables tumor cells to escape programmed cell death in multiple tumor types." (PMID 26422378, 2015). "However, no GADD45A polymorphism associated with tumor susceptibility has been reported." (PMID 26422378, 2015). "In contrast, Taxotere and/or Furtulon up-regulated some genes that are related to the induction of apoptosis (GADD45A, GADD45B, etc), cell cycle arrest (p21CIP1, VDUP1, BTG, etc), and tumor suppression." (PMID 15656911, 2005).
tumor (continued). "According to the immunohistochemistry score, Gadd45a was expressed at higher levels in tumor tissues than in normal tissues." (PMID 36821012, 2023). "The hub genes in nontumour tissues are GADD45A and IL-36G, while the hub genes in tumour tissues are POSTN and APOH." (PMID 36065314, 2022). "Growth arrest and DNA damage-inducible alpha (GADD45A) mediates the response to physiological and environmental stress by regulating cell cycle arrest, cell survival, and apoptosis and acts as a tumor suppressor in a series of cancers 5,6." (PMID 35281859, 2022). "The color reaction/positive staining of GADD45A was observed in 419 tumor tissue samples and 116 adjacent non-neoplastic tissue samples." (PMID 30128181, 2018). "To investigate the influence of GADD45A expression on tumor growth in vivo, we injected mice with IDH1R132HU87-Luc2 cells that stably expressed either pcDNA3.1-GADD45A or GADD45A-siRNA and monitored tumor growth." (PMID 28445981, 2017). "The present analysis showed, for the first time, that the anti-tumor effect of fisetin was mediated mainly through modulation of multiple signaling pathways and via activation of CDKN1A, SEMA3E, GADD45B and GADD45A and down-regulation of TOP2A, KIF20A, CCNB2 and CCNB1 genes." (PMID 28052097, 2017). "Until now, the GADD45 gene family, including GADD45A, GADD45B and GADD45G, has been recognized as stress sensors that modulate the response of mammalian cells to genotoxic and physiological stresses and the process of tumor formation and progression." (PMID 23110778, 2012). "Consequently, mice lacking GADD45A exhibit genomic instability and reduced apoptosis of malignant cells, and, thus, are more prone to tumor development." (PMID 40301189, 2025). "GADD45A, a member of the Growth Arrest and DNA Damage-inducible 45 family (which also includes GADD45B and GADD45G), is a critical stress sensor mediating various cellular responses such as DNA repair, cell cycle arrest, and apoptosis, which are significant in tumor initiation and progression." (PMID 39458909, 2024). "Moreover, DK1 also enhanced the expression of several other tumor suppressor genes that are related to this pathway such as FOXO, TP73, CDKN1A, Caspase, CYCS, and GADD45A while impeded the expression of other proto-oncogenes namely PIK3R3, BCL-2, IGFBP2, HGF, and FGF." (PMID 34204873, 2021). "Beyond that, a study showed that GADD45A promotes Myc-driven breast carcinogenesis by negatively regulating matrix metalloproteinase 10 (MMP10) through GSK-3β (Glycogen synthase kinase 3 beta)/β-catenin signaling, resulting in increased tumor vascularization and growth." (PMID 30128181, 2018). "Thus, it appears likely that Wnt-independent effects of ICG-001 may at least partially be mediated through upregulation of p21, Gadd45A, and JDP2, resulting in strong impairment of tumor-specific features in pedHGG cells." (PMID 28460484, 2017). "Indeed, wedelolactone could activate PRC2 downstream tumor suppression genes such as DAB2IP, ADRB2, CDKN2A and GADD45A, thus it serves as a mechanism for its inhibition on PRC2-dependent cancer cells." (PMID 25944687, 2015).
cancer (139 papers, 2006 to 2025). A tumor composed of atypical neoplastic, often pleomorphic cells that invade other tissues. "Elevated levels of SOX4, DDIT3, and GADD45A—genes implicated in stress response, DNA repair, and cancer stem cell maintenance—further suggest engagement of transcriptional mechanisms linked to cancer progression, therapy resistance, and recurrence." (PMID 40756515, 2025). "By its involvement in the DNA damage repair pathway, GADD45A can play an important role in the response to cancer chemotherapies that cause DNA damage, such as the DNA alkylating agent Cisplatin." (PMID 36497117, 2022). "It contributes to the transcriptional activation of several genes, including BCL2-associated X(BAX) and GADD45A, which in turn stop cancer cell proliferation and delete or diminish cancer cell tumorigenic potential." (PMID 35631261, 2022). "In various cancer cells, including BC, GADD45A repression was strongly associated with increased cancer cells survival, uncontrolled proliferation, and carcinogenesis." (PMID 35631261, 2022). "GADD45A can reduce the risk of cancer by blocking the G2/M phase of the cell cycle, repairing DNA and promoting apoptosis." (PMID 32181475, 2020). "It was found that Gadd45α-deficient mice increased cancer susceptibility, and it was also observed that Gadd45 was frequently deficient in tumor cells." (PMID 29225771, 2017). "However, molecular pathways underlying this protective role of GADD45A in cancer are not completely known." (PMID 32013256, 2020). "GADD45A is rapidly induced in response to DNA damage, and studies have shown its importance in apoptosis induction by anti-cancer agents." (PMID 39874307, 2025). "Pyrosequencing of GADD45A in an American serum cohort (PCa patients n = 34 and patients with benign lesions n = 48) also confirmed significantly higher methylation in cancer patients compared to those with benign cases (p < 0.01)." (PMID 41008642, 2025). "It is also reported that GADD45A increases in cancer cells after the application of many anticancer treatments and helps to increase the effectiveness of the treatments used." (PMID 39838121, 2025). "Conversely, inactivation of GADD45A can make cancer cells more resistant to radiation, impacting treatment outcomes." (PMID 39498386, 2024). "Among the 102 feature genes, eight genes (MYLK, GADD45A, ACADM, UQCR11, TST, PTCD3, SOD1, CD151) were significantly enriched in the cancer hallmark of adipogenesis." (PMID 36905391, 2023). "Subsequently, ectopic GADD45A promoted PTX-induced cell apoptosis, sensitizing resistant cells to PTX therapy, and insufficiency of GADD45A in original cancer cells induced resistance to PTX treatment." (PMID 37291119, 2023). "GADD45A also exhibits a changed splicing pattern in cancer cells, with the shorter splice form inhibiting cell cycle progression during stress." (PMID 35187582, 2022). "In cancer, Gadd45a was found induce Gadd45a-dependant apoptosis in response to NF-kappa B signaling and serves as important links between NF-kappa B and MAPK signaling." (PMID 36561300, 2022).